TNF (tumor necrosis factor)
Diseases named in the same sentence as TNF in open-access papers (continued):
Sharing a sentence is not in itself a finding about the gene and the disease.
Obesity (continued). "Levels of mRNA encoding TNF-α, a putative mediator of insulin resistance associated with obesity and activation of an nuclear factor kappa-B (NF-κB) response element – enhanced Green Fluorescent Protein (EGFP) reporter transgene (NF-κBEGFP) were used as biomarkers of inflammation." (PMID 20808947, 2010). "A variety of adipocyte-derived biologically active molecules have been identified, including leptin, resistin, TNF-α, and IL-6, that may contribute to obesity-linked metabolic abnormalities." (PMID 19254366, 2009). "Increased serum concentrations of TNF, NO,and IL-6 are strongly associated with obesity, and proinflammatory cytokines sourced from adipose tissueincluding TNF, and IL-6 are among several important factors that participate inthe development of insulin resistance and type 2 diabetes mellitus." (PMID 18309368, 2008). "Tumor necrosis factor alpha (TNFα) is implicated in a wide variety of pathological and physiological processes, including chronic inflammatory conditions, coronary artery disease, diabetes, obesity, and cachexia." (PMID 18070349, 2007). "Even though predominantly an inflammatory cytokine, it has been implicated in conferring insulin resistance in peripheral tissues in a number of different disease states associated with elevated systemic TNF-alpha levels, such as obesity, cancer, and infection." (PMID 17140429, 2006). "Insulin resistance, which is associated with TNFα overactivity in obesity, might also influence lipid metabolism." (PMID 16803616, 2006). "Increased blood concentrations of TNF-α and IL-6 were associated with obesity and type II diabetes." (PMID 15904534, 2005). "The increased concentrations of TNF-α and IL-6, associated with obesity and type 2 diabetes, might interfere with insulin action by suppressing insulin signal transduction, which in turn might promote inflammation." (PMID 15904534, 2005). "Indeed, obesity is associated with elevated levels of cytokines whose systemic administration leads to impaired glucose homeostasis, such as TNFα and IL-6, which we show here to mediate the inflammatory induction of human resistin." (PMID 15578112, 2004). "Here we demonstrated that oral administration of C.B effectively alleviated HFD-induced obesity and associated metabolic disorders, including glucose intolerance and hyperlipidemia, as well as systemic inflammation, as evidenced by reduced levels of LPS, TNF-α, and IL-1β." (PMID 40415947, 2025). "In summary, our results emphasize that dietary antioxidants may influence the relationship between TNF-α -308 G/A gene polymorphisms and insulin levels in individuals with obesity by mitigating oxidative stress, which may help reduce the effects on inflammatory pathways." (PMID 40732969, 2025). "Obesity and overweight may worsen RA symptoms and outcomes due to increased inflammation caused by pro-inflammatory cytokines secreted by adipose tissue (e.g., IL-6 and TNF-α)." (PMID 40597453, 2025). "Considering TNF-α among the inflammatory cytokines and reported to be associated with obesity, future studies about inflammatory cytokines and the underlying mechanisms of adipose tissue inflammation in AA patients may contribute to understanding the relationship between body fat and this disease." (PMID 41470125, 2025). "Obesity is associated with the presence of prothrombotic factors (e.g., fibrinogen, homocysteine), inflammatory markers (e.g., interleukin-6 (IL-6), tumor necrosis factor-alpha (TNF-α), C-reactive protein (CRP)), and adipocytokines (e.g., leptin, adiponectin))." (PMID 39857920, 2025). "Obesity, now classified as a low-grade chronic inflammatory state, is linked to elevated circulating levels of pro-inflammatory cytokines including interleukin-6 (IL-6), tumor necrosis factor-alpha (TNF-α), and leptin, which can adversely affect periodontal tissues and exacerbate disease severity." (PMID 40922027, 2025).
Obesity (continued). "Furthermore, obesity is associated with chronic inflammation and elevated levels of cytokines, such as TNF-α, interleukin-1 beta (IL-1β), interleukin-6 (IL-6), and adipokines (e.g., leptin), which support tumor cell proliferation, angiogenesis, and TME modulation." (PMID 41228278, 2025). "Additionally, obesity is associated with a state of chronic low-grade inflammation, wherein pro-inflammatory cytokines, such as tumor necrosis factor-alpha (TNF-α), interleukin-6 (IL-6), and interleukin-1 (IL-1), are upregulated, further exacerbating metabolic dysregulation." (PMID 39974837, 2025). "Of note, it is essential to highlight that the use of cytokines as biomarkers of MASLD may face some critical challenges in the clinical context: (a) many cytokines implicated in MASLD, such as IL-1β, TNF-α, and IL-6, are also involved in obesity, IR, and T2DM, which usually coexist with MASLD." (PMID 40794228, 2025). "Notably, only TNF-α and leptin were associated with MetS among the obesity group." (PMID 39837875, 2025). "Obesity is a risk factor for periodontal disease due to the secretion of pro-inflammatory cytokines such as TNF-α from adipose tissue, which may induce increased susceptibility to periodontal disease through exacerbated infection with periodontal pathogens and a hyper-inflammatory state." (PMID 40342576, 2025). "Besides the overproduction of cytokines such as IL-6 and TNF-α within the inflamed mammary microenvironment, which has deleterious effects on mammary gland function, obesity is linked to increased synthesis of serotonin in the mammary gland by upregulating tryptophan hydroxylase 1 (TPH1)." (PMID 40868103, 2025). "Some research conveyed that obesity could lead to a proinflammatory environment dominated by high levels of C-reactive protein, interleukin-6, and tumor necrosis factor-α, as well as a relative deficiency of protective immune cell types in the endometrium, which may contribute to EC risk." (PMID 40538813, 2025). "Inflammation associated with obesity is primarily caused by excess nutrients that activate the signaling pathways localized in adipose tissue triggering inflammatory responses resulting in the increased secretion of cytokines such as IL-6, TNF-α, IL-17, and IL-23; c-JNK; and NF-κB." (PMID 39845239, 2024). "It has been proposed that an increase in the secretion of interleukin-6 (IL-6) and tumor necrosis factor-alpha (TNF-α) in adipose tissue under conditions of obesity-induced insulin resistance could underlie the associations of insulin resistance with endothelial dysfunction and coagulopathy." (PMID 39199353, 2024). "The excess visceral adiposity, typical of obesity, is responsible for increasing the number of molecules that induce cancer pathogenesis, such as leptin, resistin, and other adipokines, in addition to pro-inflammatory cytokines such as IL-1, IL-6, IL -8, and TNF-α, elevating the risk of neoplasms." (PMID 39042663, 2024). "This is mainly because these polyphenols can inhibit the activity of inflammatory factors such as TNF-α and NF-κB, reduce oxidative stress, and upregulate antioxidant and anti-inflammatory molecules, thereby alleviating chronic inflammation associated with obesity." (PMID 39599620, 2024). "In addition, a considerable reduction in obesity-associated low-grade chronic inflammation (TNF-α, IL-6, IL-1β plasma levels) could be observed." (PMID 39765824, 2024). "Evidence from the literature indicates that obesity adversely affects the clinical response to biological therapies in patients with psoriasis, with anti-IL-17 and anti-IL-23 therapies showing greater susceptibility to reduced efficacy in individuals with a higher BMI compared to anti-TNF agents." (PMID 39768570, 2024). "Our data indicate that elevated TNF-α levels in obesity may directly increase cardiovascular risk." (PMID 39149648, 2024).
Obesity (continued). "Furthermore, the low-grade systemic inflammation caused by some molecules such as interleukin-6 (IL-6), IL-1β, TNFα, leptin, and adiponectin may play a role in obesity association with KOA." (PMID 39472918, 2024). "Obesity is a chronic inflammatory disorder, associated with adipocyte hypertrophy and secretion of pro-inflammatory cytokines, such as interleukin (IL)-6, IL-1, IL-8, and tumor necrosis factor (TNF)-α, as well as adipokines such as leptin, adipsin, resistin, and visfatin by adipose tissue." (PMID 38864906, 2024). "It is established that obesity is associated with a state of chronic inflammation in the patient, characterized by the accumulation of M1-polarized macrophages, Tregs, and the secretion of proinflammatory factors, including TNF-α, IL-6, IL-1β, and leptin, which have all been linked to CRC." (PMID 39201522, 2024). "Research has shown higher serum TNF-α levels in obese individuals than in individuals with normal weight.This physiological activity may be associated with the action of leptin produced during obesity." (PMID 39564133, 2024). "TNF-α, a crucial contributor to insulin resistance, suppresses the activity of insulin receptor tyrosine kinase and causes the phosphorylation of insulin receptor substrate 1, weakening insulin signaling, which in turn triggers metabolic disorders associated with obesity." (PMID 39116149, 2024). "Macrophage polarization and its derived cytokines, including TNFα and a series of interleukins, are associated with the pathogenesis and progression of many inflammatory and autoimmune diseases, such as antimicrobial defense, anti-tumor immune responses, obesity and metabolic diseases." (PMID 37049395, 2023). "Furthermore, TNF-α and IL-6 also have been highlighted to be responsible for the association between obesity and asthma, since they could enhance the production of IL-4 and IL-5, being both found raised in eosinophilic asthma." (PMID 37920579, 2023). "Obesity/insulin-resistance may be the main cause of sleep apnea, which in turn may accelerate these metabolic abnormalities because of the gradual rise of cytokines, such as IL-6 and TNF-α." (PMID 37215125, 2023). "Furthermore, the low-grade systemic inflammation associated with obesity not only increases periodontal inflammation but promotes bone resorption processes caused by the recruitment of immuno-inflammatory cells and certain cytokines (IL-1β, TNF)." (PMID 37894804, 2023). "It is well established that adults with obesity may also have elevated levels of systemic inflammation, and that weight loss interventions decrease circulating inflammatory markers such as interleukin-6 (IL-6) and tumor necrosis factor-alpha (TNF-α)." (PMID 38068805, 2023). "Interestingly, we frequently observed that many circRNAs were involved in regulating Il6 expression in astrocytes exposed to TNF-α and Chol, indicating that obesity-linked circRNAs may be key factors that regulate the IL-6 cytokine production in astrocytes." (PMID 37047207, 2023). "Increased BMI and obesity are strongly associated with changes in the physiological function of adipose tissue, leading to enhanced secretion of adipocytokines and inflammatory factors including leptin, interleukin-6 (IL-6), tumor necrosis factor-α (TNF-α), MCP-1, resistin, and hs-CRP." (PMID 37147659, 2023). "Additionally, obesity may result in the increased secretion of pro-inflammatory cytokines, including TNF-α, IL-6 and CRP, causing chronic inflammation, and the impaired quality and development of embryos." (PMID 36742394, 2023). "Obesity can change the cellular composition of adipose tissue, accompanied by an increased infiltration by macrophages and other immune cells, which is linked to increased cytokine secretion, predominantly TNF-α, as well as a changed T-cell population, leading to low-grade and chronic inflammation." (PMID 37672078, 2023).
Obesity (continued). "Therefore, TNF-α from obese ATMs may serve as a strong stimulator for abnormal HGP in obesity and associated diabetes mellitus." (PMID 36091076, 2022). "Obesity-associated hypoxia was proposed as a key initiator of AT dysregulation and meta-inflammation, through up-regulation of proinflammatory mediators in adipocytes and macrophages, such as TNFα, IL-1, IL-6, CCL2, inducible nitric oxide synthase (iNOS), and others." (PMID 35543703, 2022). "Maternal prepregnancy obesity or excessive weight gain during pregnancy would lead to chronic systemic inflammation and placental inflammatory response, causing increased concentrations of pro-inflammatory cytokines such as IL-6, IL-8, tumor necrosis factor-α (TNF-α) and C-reactive protein (CRP)." (PMID 36364875, 2022). "Obesity is considered a chronic inflammatory condition that is associated with dysregulated adipose tissue production of pro-inflammatory adipokines, such as the interleukin (IL) family, tumor necrosis factor (TNF) system, monocyte chemoattractant protein-1 (MCP-1), resistin, and leptin." (PMID 36235704, 2022). "The factors related to obesity that negatively influence bone mass are mainly associated with an increase in the percentage of fat mass since obesity is a proinflammatory state that is associated with the secretion of a series of cytokines (IL-6, TNF-α) and adipokines (adiponectin, leptin...)." (PMID 35458178, 2022). "Furthermore, TNF is associated with obesity and T2D and correlates with glycated hemoglobin." (PMID 36225181, 2022). "Furthermore, obesity is associated with impaired ovarian function, poor oocyte quality and decreased reproductive performance by elevated proinflammatory cytokines, such as interleukin 6 (IL-6) and TNFα as well as oxidative stress." (PMID 35897496, 2022). "Importantly, TNF-α deficiency provided protection from obesity-induced insulin resistance in mice." (PMID 36091076, 2022). "Excess visceral fat developed in obesity has been shown to secrete more adipokines and chemokines that promote insulin resistance, macrophage infiltration and activation, and is associated with elevated inflammatory markers such as interleukin 6 (IL-6) and tumor necrosis factor-α (TNF-α)." (PMID 35276910, 2022). "Obesity-induced in insulin metabolism and sex hormones, activation of growth factor signaling, induction of specific lipids, and secretion of various adipokines and inflammatory cytokines such as tumor necrosis factor-α, and interleukin-6 are associated with an increased risk of mortality." (PMID 35802728, 2022). "In addition, in previous studies, it has been observed that TNFα, an obesity marker related to the obesity-associated inflammatory state, reduces protein levels of GLUT-4, adiponectin and phospho-AMPK, besides reducing glucose uptake by stromal endometrial human cells." (PMID 35409282, 2022). "Furthermore, adipose tissue inflammation, which is an important factor in the development of obesity and metabolic syndrome, has been associated with decreased DNA methylation of the gene encoding tumor necrosis factor (TNF) in subjects with metabolic syndrome compared to healthy subjects." (PMID 36613595, 2022). "Moreover, it was recently documented that TNF-α, a member of the adipokine family, may be associated with hyperandrogenism, increased insulin resistance, and obesity, which are common factors in the pathogenesis of PCOS." (PMID 36406137, 2022). "Conversely, as obesity progresses, most ATMs are converted from an anti-inflammatory (M2-like) phenotype into a pro-inflammatory (M1-like) phenotype, secreting pro-inflammatory cytokines (such as TNF-α, IL-1β) and causing localized and systemic chronic low-grade inflammation, especially in WAT." (PMID 35563728, 2022).
Obesity (continued). "In this case, MTF could enhance the insulin-sensitizing effect of adiponectin and/or decrease the levels of molecules related to the TNFα signaling pathway and therefore diminish the insulin-repressor effect of this pro-inflammatory cytokine associated with obesity." (PMID 35409282, 2022). "Thus, obesity is complemented by inflammation, which promotes proinflammatory cytokine expression, including tumor necrosis factor-α (TNF-α), IL-6, and IL-1β, which may be linked to adipose tissue expansion." (PMID 35164043, 2022). "Obesity-associated AT inflammation is characterized by the generation and secretion of multiple inflammatory cytokines and chemokines, including but not limited to interleukin-6 (IL-6), tumor necrosis factor-α (TNF-α), IL-1β, IL-18, and monocyte chemoattractant protein-1 (MCP-1)." (PMID 34680216, 2021). "Since the observed changes could partially be attributed to TNF-α and IL-6 activity, an anti-inflammatory therapy might be a promising early therapeutic prevention option, especially in high-risk patients, such as those suffering from obesity or T2DM." (PMID 34064969, 2021). "Adiponectin, which is reduced in plasma in obesity, significantly stimulated growth factor and extracellular matrix expression, proliferation, and in vitro wound healing, significantly reduced constitutive tumor necrosis factor-α expression and caused significant upregulation of its own expression." (PMID 34948136, 2021). "Previous studies showed that insulin resistance/hyperinsulinemia, abnormal endogenous estrogen signaling, inflammatory cytokines, and adipocytokines (IL-6, TNF-α, adiponectin, visfatin, and leptin) may be the main mechanisms behind obesity that is associated with EC." (PMID 34975754, 2021). "Besides, TNF-α is suggested to be associated with obesity-related insulin resistance." (PMID 33997011, 2021). "HFD-induced obesity is associated with the infiltration of macrophages into the adipose tissue, which accounts for a higher concentration of proinflammatory cytokines such as TNF-α and IL-6 in the adipose tissue, as well as an increase in inducible nitric oxide synthase (iNOS) expression." (PMID 33498671, 2021). "Obesity is considered as a condition of chronic subacute systemic inflammation which is associated with an increased synthesis of pro-inflammatory cytokines by both adipocytes and macrophages of the adipose tissue (interleukin (IL)-1β, tumor necrosis factor-α (TFNα), CRP)." (PMID 34621378, 2021). "Since elevated levels of IL-1β and TNFα have been previously linked to obesity-induced inflammation and the development of insulin resistance in adipose tissue adipokines, we investigated whether these two agents interact to trigger IL-6 production in adipocytes." (PMID 34831450, 2021). "Obesity is accompanied by chronic inflammation associated with hypoxia and adipocyte dysfunction, which resultsinappearance of pro-inflammatory cytokines such as TNF-alpha, IL-6, MCP-1, IL-1 beta and IL-17A, likely to play a role in lung injury associated with ARDS." (PMID 34960696, 2021). "Inflammatory markers that are increased in obesity, such as tumor necrosis factor-α (TNF-α) and interleukin-6 (IL-6), were associated with increased risk of incident ccRCC, but whether these inflammatory pathways play a causal role in the pathogenesis of ccRCC has not been definitively established." (PMID 34564424, 2021). "Thus, increased infiltration of proinflammatory macrophages could contribute to the reduced myoblast differentiation, associated with obesity-induced muscle loss by secreting the inflammatory cytokine TNFα via p38 signaling pathway." (PMID 32872540, 2020). "To verify that expression of the genes analyzed in general was not static but could be modified by other stimuli, we subjected the cells to other obesity-associated stimuli (TNFα, IFNγ) or inflammatory stimuli (Pam3Cys, LPS) and observed various changes in gene expression." (PMID 32849273, 2020).